CRP (C-reactive protein)
Diseases named in the same sentence as CRP in open-access papers (continued):
Sharing a sentence is not in itself a finding about the gene and the disease.
systemic inflammatory response syndrome (180 papers, 2005 to 2026). SIRS is a serious condition related to systemic inflammation, organ dysfunction, and organ failure. "CPB is associated with a systemic inflammatory response syndrome (SIRS) which makes the usual markers of infection such as CRP difficult to interpret." (PMID 35989325, 2022). "High CRP levels are also linked to severe shock, systemic inflammatory response syndrome, and multiple organ dysfunction syndrome." (PMID 36465942, 2022). "Previous studies have showed that CRP and IL-6 level was associated with the development of systemic inflammatory response syndrome (SIRS)." (PMID 33478333, 2021). "During the early post-traumatic period, the release of danger-associated molecular pattern by injured cells results in systemic inflammatory response syndrome (SIRS) which is characterized by increased levels of CRP and cytokines." (PMID 31805967, 2019). "CRP not only reflects the extent of the infection but may also be linked to systemic inflammatory response syndrome (SIRS) resulting from pneumonia." (PMID 41357512, 2025). "Patients receiving lactated Ringer's demonstrated greater reductions in inflammatory markers, including C-reactive protein and white blood cell counts, as well as reduced persistence of systemic inflammatory response syndrome and shorter hospital stays." (PMID 42158793, 2026). "In the context of the separation of sepsis from systemic inflammatory response syndrome (SIRS), the diagnostic superiority of PCT over CRP has been reported." (PMID 37835833, 2023). "All three participants who received an IMP experienced a systemic inflammatory response syndrome, consisting of pyrexia, malaise, increased breathlessness and fatigue, with corresponding increases in serum CRP and platelets." (PMID 36057634, 2022). "Systemic inflammatory response syndrome plus CRP was more accurate than systemic inflammatory response syndrome plus IL-6 (AUC 0.79 vs. 0.72) for the prediction of SAP." (PMID 36467730, 2022). "Continuous infusion of ghrelin after esophagectomy reduces the duration of systemic inflammatory response syndrome (SIRS) by lowering C-reactive protein and IL-6." (PMID 35454106, 2022). "Rather than using individual markers, one study assessed leukocyte number, creatinine levels, CRP levels, core temperature, urine production and systemic inflammatory response syndrome components." (PMID 34070593, 2021). "CRP is an acute phase protein, which will be raised in conditions that provoke a systemic inflammatory response syndrome (SIRS)." (PMID 33779823, 2021). "At the systemic level, a low lymphocyte count is an indication of a poor systematic immune response against the infection, whereas a high c-reactive protein level is an early indicator of systemic inflammatory response syndrome." (PMID 33627118, 2021). "Elevated blood concentrations of CRP upon ICU admission are correlated with an increased risk of organ failure and death and persistent systemic inflammatory response syndrome is predictive of hospital-acquired infection in trauma patients." (PMID 31805967, 2019). "Sequential Organ Failure Assessment (SOFA) score; systemic inflammatory response syndrome score; white blood cell count; and serum C reactive protein, procalcitonin (PCT), interleukin-6 (IL-6), lactate, albumin, and hemoglobin levels were recorded." (PMID 25460569, 2014). "Clinical patterns of organ dysfunction correlate strongly with the inflammatory response, and early indicators such as systemic inflammatory response syndrome duration, rising blood urea nitrogen, hemoconcentration, and increasing CRP provide useful predictors of disease severity." (PMID 41378273, 2025). "The ratio reflects two important pathophysiological processes: the level of CRP indicates the degree of systemic inflammatory response syndrome due to infection, while the level of ALB reflects nutritional status, hepatic synthetic function, and the degree of an underlying catabolic condition." (PMID 41426582, 2025).
systemic inflammatory response syndrome (continued). "During the early postoperative period, CRP levels may rise due to systemic inflammatory response syndrome (SIRS)." (PMID 41007066, 2025). "In this context, a pilot study demonstrated that, compared to normal saline, Ringer's lactate administered for 24 hr significantly reduced the occurrence of systemic inflammatory response syndrome and C-reactive protein levels in patients with acute pancreatitis subjected to fluid resuscitation." (PMID 38962578, 2024). "Interestingly, immature granulocytes are associated with early-stage infections and have been shown to be better markers than CRP and IL-6 for systemic inflammatory response syndrome." (PMID 37147304, 2023). "Finally, levels of acute-phase proteins, including the C-reactive protein (CRP) and fibrinogen, are usually altered, indicating a severe systemic inflammatory response syndrome." (PMID 33841437, 2021). "Patients with primary myelofibrosis (PMF) have been shown to share both clinical symptoms and laboratory abnormalities with patients with systemic inflammatory response syndrome, such as elevation in the erythrocyte sedimentation rate, C-reactive protein (CRP), IL-1β, IL-6, IL-8, and TNF." (PMID 34140953, 2021). "In patients with subarachnoid hemorrhage, nonconvulsive seizures were independently associated systemic inflammatory response syndrome characterized by higher tumor necrosis factor receptor and high-sensitivity C-reactive protein serum levels." (PMID 32764270, 2020). "Markers of inflammation used in clinical practice to monitor sepsis syndrome, such as C-reactive protein, procalcitonin, and D-dimer, were elevated in 557/576 (96.7%), 413/576 (71.7%), and 469/476 (98.5%) of participants, respectively, and were significantly higher in those who died." (PMID 31276515, 2019). "As the systemic inflammatory response syndrome with high preoperative c-reactive protein levels has been reported as a poor prognostic factor for pancreatic cancer, they suggested that an enlarged LN might be associated with systemic inflammation." (PMID 31640240, 2019). "Although several clinical and laboratory predictors exist - including systemic inflammatory response syndrome (SIRS), C-reactive protein (CRP), creatinine, blood glucose, and hematocrit - these parameters alone are limited in accuracy." (PMID 41450354, 2025). "Compared to other biomarkers, a recent randomized controlled trial confirmed CRP to be a robust parameter for differentiating between septic and non-septic patients with systemic inflammatory response syndrome (SIRS)." (PMID 38570375, 2024). "EN with DFs consistently reduced systemic inflammatory response syndrome (SIRS) and C-reactive protein (CRP) levels in critically ill patients compared to standard EN." (PMID 37299452, 2023). "Ma's research showed that ω-3 PUFAs downregulated CRP levels and reduced the duration of the systemic inflammatory response syndrome (SIRS)." (PMID 35910071, 2022). "PCT, IL-6 and CRP cannot be utilized to differentiate Systemic Inflammatory Response Syndrome (SIRS) from infection, in patients who receive ATG or similar within up to three days after the application of the drug." (PMID 26543528, 2015). "But for patients with cirrhosis, the prognostic capabilities of conventional parameters such as systemic inflammatory response syndrome (SIRS) and C-reactive protein (CRP) are relatively limited." (PMID 24466280, 2014). "Our aim was to evaluate the diagnostic value of temperature, C-reactive-protein (CRP), and Systemic Inflammatory Response Syndrome (SIRS) to identify bacteraemic patients in the Medical Emergency Department (MED)." (PMID 25027551, 2014). "The result showed that patients who received saline 0.9% appeared to have higher C-reactive protein (CRP) and systemic inflammatory response syndrome (SIRS) levels." (PMID 24164963, 2013).
systemic inflammatory response syndrome (continued). "Furthermore, biomarkers like CRP and PCT often lack sensitivity and specificity in differentiating complex conditions, such as sepsis versus systemic inflammatory response syndrome (SIRS), or between ventilator-associated tracheobronchitis and pneumonia." (PMID 40137168, 2025). "Circulating CgA levels correlate with serum inflammatory markers like C-reactive protein (CRP), procalcitonin, IL-1β, IL-6, IL-8/CXCL8, IL-17C, or TNF in conditions such as gastritis, IBD, chronic heart failure or systemic inflammatory response syndrome." (PMID 40370467, 2025). "In trauma, systemic inflammatory response syndrome (SIRS), or severe burns, insulin reduces pro-inflammatory mediators (TNF-a, IL-6, CRP, IFN-y, IL-18)." (PMID 39838305, 2025). "Thus, CRP may contribute to POPF by activating systemic inflammatory response syndrome." (PMID 39717925, 2025). "Several other inflammatory indicators, including systemic inflammatory response syndrome (SIRS), C-reactive protein (CRP), and MELD scores, have prognostic value in liver disease but also have limitations." (PMID 40114845, 2025). "The primary mechanism of organ failure in SAP patients is systemic inflammatory response syndrome (SIRS), which leads to the accumulation of inflammatory mediators and metabolic toxins (e.g., IL-6 and C-reactive protein)." (PMID 40324238, 2025). "Other important predictors included systemic inflammatory response syndrome (SIRS), C-reactive protein (CRP), and markers of systemic inflammation and organ dysfunction." (PMID 40282920, 2025). "Ghrelin therapy was associated with a significantly shorter duration of systemic inflammatory response syndrome (SIRS) (MD: − 2.72, P = 0.0001), lower CRP level on postoperative day 3 (MD: − 3.64, P < 0.0001), and less total bodyweight loss (MD: − 1.87, P = 0.14)." (PMID 37314533, 2023). "Patients were admitted to the ICU with septic shock and with systemic inflammatory response syndrome (SIRS) already having been developed, as indicated by the high admission levels of the CRP." (PMID 35453325, 2022). "According to our study, routine laboratory tests such as CRP and WBC have insufficient accuracy in diagnosing sepsis syndrome." (PMID 33420845, 2021). "The duration (p < 0.001) and incidence (2/21 vs. 10/22, p = 0.08) of systemic inflammatory response syndrome (SIRS) and CRP levels (p = 0.05) were also reduced." (PMID 34833042, 2021). "Our goal was to assess PTX3 as a predictor of systemic inflammatory response syndrome (SIRS), death and disease severity in acute pancreatitis (AP) in comparison to C-reactive protein (CRP) and the APACHE II score." (PMID 31798002, 2019). "In this regard, elevated levels of high-sensitivity C-reactive protein (hs-CRP) or white blood cells (WBC), as part of a systemic inflammatory response syndrome (SIRS), have been shown to predict outcome and mortality, particularly in the presence of diabetes." (PMID 26599610, 2015). "Outcomes were evolution of systemic inflammatory response syndrome (SIRS) criteria, white cell count and C-reactive protein measurements, and adverse clinical outcomes." (PMID 25484622, 2014). "Published guidelines do not clearly state when blood cultures should be drawn but previous studies of emergency department patients have suggested body temperature, C-reactive-protein (CRP) and Systemic Inflammatory Response Syndrome (SIRS) as predictors of bacteraemia." (PMID 25027551, 2014). "Noteworthy, other researchers demonstrated a correlation between FGF21 level and CRP level in patients with systemic inflammatory response syndrome and had even proposed FGF21 as a non-specific marker for systemic inflammation." (PMID 38983722, 2024).
systemic inflammatory response syndrome (continued). "Fetal inflammatory response syndrome (FIRS) defined as an elevation of either fetal plasma IL-6 or C-reactive protein (CRP) above a specific cutoff value (i.e., IL-6 ≥ 11 pg/mL, CRP ≥ 200 ng/mL) is thought as the fetal counterpart of systemic inflammatory response syndrome (SIRS) in adults." (PMID 34066888, 2021). "The longitudinal assessment of procalcitonin (PCT) levels, C-reactive protein (CRP) levels, white blood cell count, blood lactate levels, IL-6 levels, Sequential Organ Failure Assessment (SOFA) score, and Systemic Inflammatory Response Syndrome (SIRS) was conducted." (PMID 25705399, 2013). "CRP is an extremely sensitive marker of inflammation that can differentiate the various stages of systemic inflammatory response syndrome in the absence of an infection." (PMID 22136422, 2011). "• CRP and components of systemic inflammatory response syndrome measured at T1 and T2 failed to predict a diminished PaO2/FIO2 ratio at T3." (PMID 16859526, 2006). "Traditional biomarkers such as C-reactive protein (CRP) and procalcitonin (PCT) have limitations in distinguishing infections from systemic inflammatory response syndrome (SIRS)." (PMID 40806991, 2025). "Meanwhile, CRP 25.99 mg/L, IL-6 > 5000.0 ng/L, and PCT 11.72 ng/ml, indicating the diagnosis of systemic inflammatory response syndrome (SIRS)." (PMID 36817796, 2023). "Among the patients suspected bacterial infection or fulfilled the criteria of systemic inflammatory response syndrome (SIRS) and patients who underwent blood culture, presepsin, procalcitonin (PCT), and C-reactive protein (CRP) at the same time were included." (PMID 36072944, 2022). "These patients may have high levels of CRP (> 100 mg/L), pathologic levels of procalcitonin (PCT), visible purulence in the joint aspirate and a tendency towards systemic inflammatory response syndrome (SIRS) with multiorgan failure (elevated heart rate, low systolic pressure)." (PMID 33619607, 2021). "Finally, in our series, we observed the absence of clinical signs of systemic inflammatory response syndrome and discrete alterations in leukocyte count and c-reactive protein." (PMID 34884300, 2021). "AESD: acute encephalopathy with biphasic seizures and late reduced diffusion; CRP: C-reactive protein; FS: febrile seizures; PCT: procalcitonin; SIRS: systemic inflammatory response syndrome." (PMID 31911824, 2019). "The positive predictive value of this practical cut-off may seem low, indicating that CRP levels also may be high in patients with a prolonged systemic inflammatory response syndrome based on severity of surgical trauma and not due to major complications." (PMID 26177542, 2015). "Although there is no established evidence of associations among CRP level, EVLWI, and BNP, we consider that systemic inflammatory response syndrome in response to the brain injury after SAH may contribute to the cardiopulmonary complications." (PMID 24818154, 2014). "The screening process involved assessing all admissions to the hospital on the basis of laboratory levels of CRP, WCC and systemic inflammatory response syndrome (SIRS) criteria." (PMID 23232151, 2012). "Many studies have shown associations between the magnitude of the C-reactive protein (CRP) response and cytokine release and post-SCT complications, and these complications might therefore best be regarded as manifestations of a systemic inflammatory response syndrome (SIRS)." (PMID 21188146, 2010). "Both C-reactive protein (CRP) and procalcitonin (PCT) levels were only mildly elevated, and there was no clinical or laboratory evidence of systemic inflammatory response syndrome (SIRS) or organ dysfunction." (PMID 40558808, 2025).
systemic inflammatory response syndrome (continued). "SIRS, Systemic inflammatory response syndrome; WBC, white blood cell; PCT, procalcitonin; CRP, C-reactive protein; SOFA, Sequential Organ Failure Assessment; APACHE II, Acute Physiology and Chronic Health Evaluation II; AST, aspartate aminotransferase; 2ULN, two-time upper limit normal." (PMID 34055545, 2021). "Clinical studies show RL infusion during pancreatitis allows early improvement in systemic inflammatory response syndrome (SIRS) and C-reactive protein (CRP) when compared with saline infusion, but not survival." (PMID 31963691, 2020). "When the AUC of CRP and PCT was analyzed further in patients with systemic inflammatory response syndrome (SIRS) (excluding patients without SIRS from both groups), CRP still showed no inferiority to PCT in differentiating infection." (PMID 25407928, 2014). "The patient experienced systemic inflammatory response syndrome (SIRS) (high fever, marked increase in C-reactive protein and leucocytosis) with negative blood cultures." (PMID 39666259, 2024). "Although the revised Atlanta classification recommended a systemic inflammatory response syndrome (SIRS) score of > 2 for severity prediction, this is no better than the clinically pragmatic and robust modified Glasgow system and serum CRP levels." (PMID 32910276, 2021). "We did not measure circulating levels of IL-6, CRP and TNF-alpha, but we did look for overt manifestations of inflammation through the systemic inflammatory response syndrome (SIRS) criteria." (PMID 31590379, 2019).